PDK2 (pyruvate dehydrogenase kinase 2)
Description:
Kinase that plays a key role in the regulation of glucose and fatty acid metabolism and homeostasis via phosphorylation of the pyruvate dehydrogenase subunits PDHA1 and PDHA2. This inhibits pyruvate dehydrogenase activity, and thereby regulates metabolite flux through the tricarboxylic acid cycle, down-regulates aerobic respiration and inhibits the formation of acetyl-coenzyme A from pyruvate. Inhibition of pyruvate dehydrogenase decreases glucose utilization and increases fat metabolism. Mediates cellular responses to insulin. Plays an important role in maintaining normal blood glucose levels and in metabolic adaptation to nutrient availability. Via its regulation of pyruvate dehydrogenase activity, plays an important role in maintaining normal blood pH and in preventing the accumulation of ketone bodies under starvation. Plays a role in the regulation of cell proliferation and in resistance to apoptosis under oxidative stress.
Synonyms: PDKII; PDHK2
Tractability: Small molecule: an approved drug acts on it; a structure with a bound ligand is known; a high-quality ligand is known; it has a binding pocket of medium quality. PROTAC: it is named in the literature on targeted protein degradation; ubiquitination databases record sites on it; its protein half-life has been measured; a small molecule that binds it is known.
Target class: Kinase; Enzyme; Atypical protein kinase PDHK subfamily; Atypical protein kinase group; Protein Kinase
Gene: Protein-coding gene on chromosome 17 (50,094,737 to 50,112,152, forward strand). Ensembl gene ENSG00000005882.
Subcellular location: Mitochondrion matrix
Subcellular location (Human Protein Atlas): Mitochondria; Nucleoplasm
Pathways (Reactome):
Metabolism: Regulation of pyruvate dehydrogenase (PDH) complex
Signal Transduction: Signaling by Retinoic Acid
Gene Ontology:
Molecular function: ATP binding; protein binding; protein homodimerization activity; pyruvate dehydrogenase (acetyl-transferring) kinase activity; protein kinase activity
Biological process: cellular response to reactive oxygen species; cellular response to nutrient; glucose homeostasis; glucose metabolic process; insulin receptor signaling pathway; regulation of gluconeogenesis; regulation of glucose metabolic process; regulation of ketone metabolic process; regulation of pH; regulation of pyruvate decarboxylation to acetyl-CoA; cellular response to stress
Cellular component: mitochondrion; mitochondrial matrix; pyruvate dehydrogenase complex
Genetic constraint (gnomAD): Loss-of-function variants: 30 observed, 44.25 expected, observed/expected ratio (o/e) 0.68, 90% interval 0.51 to 0.92. The upper end of that interval is the gene's LOEUF score, 0.92, which puts it in group 3 of 6, group 1 being the genes least tolerant of losing a copy. Missense variants: 366 observed, 528.43 expected, observed/expected ratio (o/e) 0.69, 90% interval 0.63 to 0.75. Synonymous variants: 220 observed, 214.37 expected, observed/expected ratio (o/e) 1.03, 90% interval 0.92 to 1.15.
Homologues: Orthologues: chimpanzee PDK2 (100% identical), macaque PDK2 (100% identical), dog PDK2 (99% identical), pig PDK2 (98% identical), guinea pig PDK2 (98% identical), mouse Pdk2 (98% identical), rat Pdk2 (98% identical), zebrafish pdk2a (73% identical), zebrafish pdk2b (71% identical), Drosophila melanogaster Pdk (55% identical), Caenorhabditis elegans pdhk-2 (51% identical), rabbit PDK2 (50% identical). Paralogues in human: PDK1 (68% identical), PDK3 (67% identical), PDK4 (65% identical), BCKDK (29% identical).
Diseases named in the same sentence as PDK2 in open-access papers:
PDK2 is named in the same sentence as 63 diseases in open-access papers, as found by Europe PMC text mining. Sharing a sentence is not in itself a finding about the gene and the disease. The quoted sentences say what the papers report.
diabetes (13 papers, 2012 to 2025). "PDK2/4 deficiency suppressed the diabetes-induced lactate surge, pain-related ion channel expression, satellite glial cell activation, and macrophage infiltration." (PMID 38139032, 2023). "We found that restricting the amount of food given to WT-diabetic mice reduces blood glucose to levels found in Pdk2-deficient mice following diabetes." (PMID 33219201, 2020). "On the other hand, the diabetes-induced expression of proinflammatory cytokines such as Tnf-α, Il-1β, and Il-6 was substantially diminished by Pdk2-deficiency." (PMID 33219201, 2020). "We found that diabetes in mice enhances the hypothalamic expression of PDK2 and phosphorylated-PDH (p-PDH), causing a glycolytic metabolic shift along with substantial hypothalamic inflammation." (PMID 33219201, 2020). "The diabetes-induced increased food intake, as well as the blood and CSF glucose levels, were substantially reduced by Pdk2-deficiency following STZ injection." (PMID 33219201, 2020). "Abnormal regulation of PDC in diabetes is associated with two isoforms: PDK2 and PDK4." (PMID 33739396, 2021). "Our findings demonstrate a critical role that astrocyte-specific PDK2 plays in the hypothalamus in regulating metabolic and inflammatory pathways that contribute to the hypothalamic pathology of altered feeding behavior associated with diabetes." (PMID 33219201, 2020). "We also observed that genetic deletion or pharmacological inhibition of hypothalamic PDK2 significantly reduced diabetes-induced inflammatory markers and food intake associated with an increase in orexigenic neuropeptide and decreased anorexigenic neuropeptide expression." (PMID 33219201, 2020). "To determine whether the reduced food intake shown by Pdk2-deficient mice following diabetes is due to changes in systemic insulin or leptin levels, we collected plasma from WT and Pdk2 KO mice at 3 weeks post-STZ injection." (PMID 33219201, 2020). "Similarly, hypothalamic astrocyte-specific Pdk2 deficiency reverses the increased food intake caused by diabetes and decreases inflammation as well as the lactate level in the hypothalamus." (PMID 33219201, 2020). "Taken together, these results suggest that the PDK2-lactic acid axis might be a key component of hypothalamic inflammation and subsequent pathologies associated with diabetes." (PMID 33219201, 2020). "Furthermore, Pdk2 deficiency significantly attenuated the diabetes-induced increase in p-S293-PDH and p-S300-PDH protein levels." (PMID 33219201, 2020). "Taken together, it appears that PDK2 plays a crucial role in the hypothalamic pathogenesis of altered feeding behavior and subsequent alteration in energy metabolism associated with both type 1 and 2 diabetes." (PMID 33219201, 2020). "This indicates that astrocyte-specific PDK2 plays a critical role in hypothalamic inflammation and subsequent dysregulation of neuropeptidergic circuitry associated with altered feeding behavior in diabetes." (PMID 33219201, 2020). "Mechanistically, studies using primary astrocytes, hypothalamic neuronal cells, and electrophysiological analysis of brain slice cultures demonstrate that PDK2 is a critical regulator of metabolic homeostasis and hypothalamic pathology involved in altered feeding behaviors caused by diabetes." (PMID 33219201, 2020). "In the present study, the onset of diabetes increased the level of lactate in the hypothalamus, but lactate was significantly decreased in Pdk2-deficient animals, suggesting that increased expression of neuronal PDK2 might also contribute to accumulated lactate in the diabetic hypothalamus." (PMID 33219201, 2020). "Genetic ablation or hypothalamic inhibition of PDK2 attenuated diabetes-induced neuroinflammation, lactate surge in the hypothalamus in mice." (PMID 37396164, 2023). "In starvation and diabetes, nutritional factors and hormones regulate the expression of PDK2 and PDK4, and the body reduces the activity of PDC by increasing PDK activity." (PMID 33739396, 2021).
diabetes (continued). "In conclusion, our findings suggest that astrocytic PDK2 plays an important role in hypothalamic inflammation and consequent impairment of feeding behavior in diabetes." (PMID 33219201, 2020). "Here, we show that pyruvate dehydrogenase kinase (PDK)-2 plays a role in hypothalamic inflammation and its sequelae in mouse models of diabetes." (PMID 33219201, 2020). "Here, the authors show that astrocytic PDK2 ablation or inhibition attenuates hypothalamic inflammation in mouse models of diabetes." (PMID 33219201, 2020). "Genetic ablation or hypothalamic inhibition of PDK2 attenuates diabetes-induced neuroinflammation, lactate surge in the hypothalamus, and food intake in mice." (PMID 33219201, 2020). "Our findings reveal that PDK2 ablation or inhibition in mouse astrocytes attenuates diabetes-induced hypothalamic inflammation and subsequent alterations in feeding behavior." (PMID 33219201, 2020). "Following the onset of diabetes, the expression of PDK2 and p-PDH was significantly up-regulated in mouse hypothalamus and limited to the ARC region." (PMID 33219201, 2020). "Here, we report that astrocytic PDK2 regulates metabolic and inflammatory pathways that contribute to hypothalamic manifestations of diabetes." (PMID 33219201, 2020). "This suggests that PDK2 plays a pivotal role in hypothalamic inflammation and subsequent pathology of altered feeding behavior in diabetes." (PMID 33219201, 2020). "The crucial contribution that hypothalamic PDK2 and lactic acid production make to the pathogenesis of diabetes-induced hypothalamic inflammation and altered feeding behavior in mice was ascertained by pharmacological inhibition of hypothalamic PDK2 and LDH." (PMID 33219201, 2020). "To examine the specific hepatic effects of Pdks on diabetes, we also knocked down the Pdk2 or Pdk4 gene using specific shRNAs." (PMID 23940800, 2013). "To further investigate the role of Pdk2 and Pdk4 in the pathogenesis of diabetes in the IrsLDKO mice, we deleted either the Pdk2 or Pdk4 gene on the IrsLDKO genetic background." (PMID 23940800, 2013). "In this study, we directly assessed the involvement of Pdk2 and Pdk4 in the pathogenesis of diabetes." (PMID 23940800, 2013). "For example, recent studies have used metabolomics to reveal that restoring phenylalanine levels and modulating glutathione metabolism can identify drug targets such as AKT2 and PDK2 in diabetes and cancer models, thereby guiding precision drug design and repurposing." (PMID 40725110, 2025). "However, mice with selective deletion of Pdk2 in hypothalamic neurons showed a remarkable reduction in diabetes-induced food intake." (PMID 33219201, 2020). "PDK2 is expressed at high levels in both hypothalamic astrocytes and neurons following diabetes." (PMID 33219201, 2020). "Remarkably, ablation of astrocytic Pdk2 in the hypothalamus attenuated diabetes-induced local inflammation, characterized by increased levels of the inflammatory cytokines Tnf-α, Il-1β, and Il-6 mRNA, and proliferation and activation of GFAP-positive astrocytes and Iba-1-positive microglia." (PMID 33219201, 2020). "Remarkably, overexpression of hypothalamic PDK2 reversed the effects of Pdk2 KO on diabetes-induced Tnf-α, Il-1β, and Il-6 mRNA expression, food intake, blood glucose, and expression of Npy, Agrp, and Pomc in the diabetic hypothalamus at 3 weeks post-STZ injection." (PMID 33219201, 2020). "To further examine the role of hypothalamic PDK2 in diabetes-induced neuroinflammation and changes in feeding behavior, we assessed the effect of PDK2 overexpression in the Pdk2 KO mice by injecting (icv) PDK2-overexpressing adenovirus (Ad-PDK2-GFP) into the third ventricle." (PMID 33219201, 2020). "PDK2 is also expressed in hypothalamic neurons following diabetes induction." (PMID 33219201, 2020). "PDK2 (p = 5 × 10−6) shows a trend towards the significance, and the overexpression of this gene may be related to cancer and diabetes." (PMID 28558704, 2017).
diabetes (continued). "Our findings identify the PDK2-lactic acid axis in hypothalamic astrocytes as a promising therapeutic target for pathological hypothalamic inflammation and subsequent dysregulation of the neuropeptidergic circuit involved in altered feeding behavior in diabetes." (PMID 33219201, 2020). "In addition, mice with selective deletion of Pdk2 in hypothalamic astrocytes showed lower levels of diabetes-induced food intake, lactate surge, and Npy and Agrp mRNAs but higher levels of Pomc mRNA in the hypothalamus when compared with the AAV5-GFAP-eYFP-injected diabetic animals." (PMID 33219201, 2020). "Pdk2 and Pdk4 double knockout mice with STZ-induced diabetes reveal the attenuated DPN pathogenesis via suppressing lactate-induced inflammation." (PMID 40429808, 2025). "Both PDK2 and PDK4 isoforms are attractive metabolic targets for pharmacological interventions to treat diabetes and obesity." (PMID 31712597, 2019). "Ablation of neuronal Pdk2 in the hypothalamus did not alter diabetes-induced expression levels of Tnf-α, Il-1β, and Il-6 mRNA, or gliosis." (PMID 33219201, 2020). "Although the plasma level of ketone body was increased following STZ-induced diabetes, it was not significantly different between WT and Pdk2 KO mice." (PMID 33219201, 2020). "Unlike the roles of PDK2 and PDK4, the role of PDK1 is underexplored in obesity and diabetes." (PMID 34552205, 2021).
hepatocellular carcinoma (9 papers, 2012 to 2024). A malignant tumor that arises from hepatocytes. "It was suggested that the decrease in PDK2 levels was caused by p21 up-regulation in hepatoma cells." (PMID 30899051, 2019). "Restriction of glutamine in hepatoma cells increases the levels of cellular reactive oxygen species and reduces aerobic glycolysis and pyruvate dehydrogenase kinase 2 (PDK2) expression." (PMID 30899051, 2019). "More importantly, hsa_circ_0005397 was overexpressed in HCC tissues, which could promote hepatocellular carcinoma progression by regulating the miR-326/PDK2 axis." (PMID 38383334, 2024). "Overexpression of RORα or treatment with SR1078, the RORα activator, reduced aerobic glycolysis, down-regulated biosynthetic pathways, reduced PDK2 expression, inhibited the phosphorylation of pyruvate dehydrogenase, and subsequently shifted pyruvate to complete oxidation in hepatoma cells." (PMID 33739396, 2021). "Suppression of PDK2 inhibited hepatoma growth in a xenograft model." (PMID 33739396, 2021). "In the current study, hypoxia specifically increased PDK4 but not PDK2 in hepatoma cell lines." (PMID 23050013, 2012).
gastric cancer (7 papers, 2018 to 2024). A primary or metastatic malignant neoplasm involving the stomach. "Specifically, low expression levels of PDK2 and PDK4 were associated with a favorable response to ICB therapy in gastric cancer patients." (PMID 38832951, 2024). "miR-422a is down-regulated in gastric cancer; it can inhibit PDK2 and restore the activity of PDH, leading to an increased Warburg effect in gastric cancer cells." (PMID 36438836, 2022). "In gastric cancer cells, miR-422a-PDK2 axis is an important mediator in metabolic reprogramming, providing a promising therapeutic target for antitumor treatment." (PMID 33739396, 2021). "Mir-422a-PDK2 axis also influenced de novo lipogenesis in gastric cancer cells, which subsequently affected reactive oxygen species (ROS) and retinoblastoma protein (RB) phosphorylation levels, and cell cycle arrest." (PMID 33739396, 2021). "In gastric cancer, the expression of miR‐422a can help drive a metabolic shift from aerobic glycolysis to oxidative phosphorylation by decreasing pyruvate dehydrogenase kinase 2 (PDK2) and thereby modulate de novo lipogenesis." (PMID 34766135, 2021). "Another study found that overexpression of miR-422a in gastric cancer cells repressed its target pyruvate dehydrogenase kinase 2 (PDK2) to restore activity of the pyruvate dehydrogenase (PDH), which shifted the energy metabolism from aerobic glycolysis to oxidative phosphorylation." (PMID 35006436, 2020). "Our analysis revealed differential expression of glycolysis-related genes between gastric cancer tissues and normal tissues, with upregulation of PD-L1 and concurrent downregulation of HK1, PDK2, and PDK4." (PMID 38832951, 2024). "Activity of pyruvate dehydrogenase (PDH) can be restored via the suppression of pyruvate dehydrogenase kinase 2 (PDK2) by miR-422, that was found to be downregulated in gastric cancer." (PMID 34680164, 2021).
lung carcinoma (7 papers, 2011 to 2025). "PDK2 is upregulated in paclitaxel- or cisplatin resistant lung cancer cells compared to the parental cells and is associated with poor prognosis in patients with lung cancer." (PMID 40612109, 2025). "Increased expression of PDK2 was also found in paclitaxel-resistant lung cancer cells as compared with their parental cells." (PMID 33739396, 2021). "In this study, the role of PDK2 in mediating paclitaxel resistance in lung cancer cells was investigated using biochemical and isotopic tracing methods." (PMID 28881758, 2017). "Down-regulation of PDK2 usingsiRNA increased the sensitivity to paclitaxel of resistant lung cancer cells." (PMID 28881758, 2017). "In summary, the present study shows that PDK2 plays an important role in paclitaxel resistance, with paclitaxel-induced expression of PDK2 serving as an important mechanism for the acquired resistance of human lung cancer cells to paclitaxel." (PMID 28881758, 2017). "Moreover, combining paclitaxel withthe specific PDK2 inhibitor dichloroacetate had a synergistic inhibitory effect on the viability of paclitaxel-resistant lung cancer cells." (PMID 28881758, 2017). "Moreover, PDK2 was found to be overexpressed in HNSCC (unpublished data) as well as other cancers including lung cancer." (PMID 21283817, 2011). "In addition, since PDK inhibition was more effective in suppressing cell growth of the resistant A549-R cells than the parental A549 cells, these results suggest that PDK2 may serve as an effective target for overcoming paclitaxel resistance in patients with lung cancer." (PMID 28881758, 2017). "Down-regulation of PDK2 can increase the sensitivity of drug-resistant lung cancer cells to paclitaxel, and combining paclitaxel with dichloroacetate (DCA), the specific PDK2 inhibitor, has a synergistic inhibitory effect on the viability of paclitaxel-resistant lung cancer cells." (PMID 33739396, 2021).
breast carcinoma (5 papers, 2016 to 2022). "However, our analysis of gene expression in stroma dissected from normal and tumour tissue showed that PDK2 expression is also reduced in samples from patients with primary breast cancer." (PMID 35760868, 2022). "LDHA is associated with breast cancer resistance to paclitaxel/trastuzumab and myeloma relapse; overexpression of hexokinase 2 (HK2) is involved in cisplatin resistance in ovarian cancer cells, by enhancing autophagy and the increased expression of PDK2 is linked to paclitaxel resistance in NSCLC." (PMID 30873026, 2019).